EGF (epidermal growth factor)
Diseases named in the same sentence as EGF in open-access papers (continued):
Sharing a sentence is not in itself a finding about the gene and the disease.
cancer (continued). "Additionally, vascular endothelial growth factor (VEGF) and epidermal Growth Factor (EGF) have been reported to promote angiogenesis and cancer cell progression." (PMID 38521953, 2024). "Additionally, the overall phosphorylation assay identified 6 upregulated phosphorylated proteins in cancer related pathways such as HIF-1, PI3K-Akt, EGF/EGFR, Toll-like receptor, and JAK-STAT signalling." (PMID 38102712, 2023). "Our analysis suggests the hypothesis that other proteins that also appear as links between EGF/EGFR and our focus pathways could be candidates for drugs that can be used in combination therapy for cancer." (PMID 36996232, 2023). "The epidermal growth factor (EGF) is one of the most critical ligands of the EGF receptor (EGFR), a well-known oncogene frequently overexpressed in cancerous cells and an important therapeutic target in cancer." (PMID 37241784, 2023). "Cetuximab was able to bind to EGFR and competitively inhibited the binding to the epidermal growth factor (EGF) and other ligands, which blocked the phosphorylation of EGFR induced by ligands and mitigated the activation of the signaling pathways related to cancer development." (PMID 37371712, 2023). "Studies showed that rutin arrests the signaling pathways that promote cancer cell proliferation, such as mitogen-activated protein kinase, PI3K/Akt, Wnt/β-catenin, and epidermal growth factor signaling pathways by suppressing the transcription of their activators." (PMID 36836827, 2023). "Furthermore, M2 TAMs secrete Epidermal Growth Factor (EGF), which binds to EGFR on cancer cells, for activating their growth signaling including MAPK/ERK and PI3K/Akt pathways, promoting cell motility and invasion." (PMID 37965573, 2023). "Hence, the epidermal growth factor (EGF) and its receptor(EGFR) play a crucial role in the pathogenesis and progression of various typesof malignant tumors." (PMID 37538799, 2023). "Cancer cells release growth factors, such as FGF-2, VEGF, PDGF, EGF, TGFβ, and cytokines and chemokines, the core group consisting of CCL2, CCL5, IL-6, IL-8, as well as other soluble factors that activate fibroblasts and modulate CAF gene expression patterns and their metabolism." (PMID 37046676, 2023). "In particular, PGE2 and EGF/EGFR may synergistically promote the growth, invasion, epithelial mesenchymal transition (EMT) and stem cell like phenotype of cancer cells." (PMID 37138287, 2023). "However, in chemotaxis driven by EGF, both short Akt and ERK waves contribute to the overall motive force of cancer cells." (PMID 36829763, 2023). "Next to the lack of discrimination between healthy and cancer cells, it has been reported that 111In-labelled EGF cannot discriminate between high and moderate EGFR overexpression." (PMID 37746282, 2023). "In addition, PKM2 regulation by OGT is augmented by epidermal growth factor (EGF), which is highly expressed in various cancers to promote cell survival and proliferation." (PMID 37838167, 2023). "Endocytosis of Jacalin and ACA in cancer cells was decreased in vitro after addition of inhibitor of macropinocytosis 5-(N-ethyl-N-isopropyl) amiloride (EIPA) and increased after stimulation of macropinocytosis with epidermal growth factor (EGF)." (PMID 37535087, 2023). "Furthermore, we demonstrated the regulatory circuit among EGF signaling, CSN6 signaling, FASN expression level, and accumulation of fatty acids during cancer formation." (PMID 37202390, 2023). "Unlike normal cells, cancer cells exhibit a unique characteristic of releasing and responding to growth factors, particularly epidermal growth factor (EGF) and its receptor (EGFR) signaling." (PMID 38067626, 2023). "Moreover, several growth factors, including insulin-like growth factor 1 (IGF-1), basic fibroblast growth factor 2 (FGF2), and epidermal growth factor (EGF), can greatly activate the PI3K-AKT pathway, thereby facilitating malignant behaviors of cancers 12-16." (PMID 37496999, 2023).
cancer (continued). "In previous reports, Akt activation was found to increase the activity of A Disintegrin and Metalloproteinase 17 (ADAM17), which increases the shedding of heparin-binding EGF (HB-EGF) and amphiregulin (AREG) from the cancer cell surface, leading to EGFR activation." (PMID 37779142, 2023). "CAFs could induce angiogenesis, improve the oxygen and nutrient supply, and provide immunosuppressive cytokines to cancer cells, including TGF-β, epidermal growth factor (EGF), platelet-derived growth factor (PDGF), and fibroblast growth factor-2 (FGF-2)." (PMID 36761757, 2023). "We focused on two of these pathways—Glycolysis and gluconeogenesis and Transmembrane transport of small molecules —because of their strong PTM cluster-based links to the EGF/EGFR signaling pathway and because of the importance of metabolic adaptations in the progression to advanced cancer." (PMID 36996232, 2023). "Therefore, we withdrew the supplements to test the effect of EGF alone on the activity of RAC1 and CDC42 in these cells and compared the responses with those of the cancer cells." (PMID 37057894, 2023). "Growth factors constitute bioactive molecules, the most common of which are platelet-derived growth factor (PDGF), epidermal growth factor (EGF), and insulin-like growth factor (IGF), as well as TNFα, which can promote the proliferation of cancer cells via the NF-κB pathway." (PMID 37958980, 2023). "EGF, one of the most abundant growth factors in the tumour microenvironment, can be produced by cancer cells and non-cancerous cells such as endothelial cells, mesenchymal stromal cells, and macrophages." (PMID 35681586, 2022). "Since this was first demonstrated by EGF to EGFR-mediated signaling pathways, we now understand that similar signaling processes play a vital role in other key processes, such as migration of tumor cells and cancer metastasis." (PMID 35847914, 2022). "Rutin has been shown to target cancer cells by providing anti-inflammatory effects, suppressing pro-inflammatory secretions, altering transcription factors, and modulating cancer signaling pathways (MAPK, PI3K/Akt, epidermal growth factor (EGF), and Wnt/catenin)." (PMID 36295828, 2022). "EGF favours epithelial-mesenchymal transition (EMT) and it maintains cancer stemness." (PMID 34955078, 2022). "We present novel single-molecule total internal reflection fluorescence microscopy of (i) EGF and EGFR in living cancer cells, (ii) the action of anti-cancer drugs that separately target EGFR and human EGFR2 (HER2) on these cells and (iii) EGFR–HER2 interactions." (PMID 35612280, 2022). "As pyruvate kinase M2 (PKM2) is the rate-limiting enzyme controlling the final step of glycolysis and serves as a major regulator of the Warburg effect in different cancer cells, the regulation of PKM2 by EGF, particularly in high EGFR–expressing cells, is thus of great importance." (PMID 35931120, 2022). "Moreover, the molecular function of PRELP as a regulator of major cancer-related pathways of TGF-β, EGF, and Wnt also strongly indicates that PRELP suppression is not just consequence of RB development." (PMID 36230849, 2022). "Last, but not least, minocycline has been used in cancer patients undergoing treatment with epidermal growth factor inhibitors as a prophylactic agent for dermatological toxicity, without causing side effects." (PMID 36009536, 2022). "In the bone metastasis stage, cancer cells release PTHrP to promote osteoblasts for the secretion of RANKL, and then RANKL further stimulates osteoblast activation and erodes bone tissue, thus producing a large amount of EGF and calcium ions." (PMID 36015599, 2022). "Therefore, the CICs in the PDAC organoids were differentiated into ductal-like cancer cells via the Wnt/NOTCH inhibition and EGF pathway." (PMID 35673567, 2022).
cancer (continued). "JAK/STAT, VEGF and EGF/EGFR-mediated pathways are primarily involved in developmental stages but, interestingly, deregulation of these pathways has been widely documented during different stages of cancer." (PMID 36615262, 2022). "Together, our study shows that HD6 may compete with EGF to bind to EGFR and interrupt cancer progression in CRC." (PMID 34975297, 2022). "The stemcell niche environment is rich in other growth factors, such as fibroblast growth factor-2 (FGF-2) and epidermal growth factor (EGF), that induce Id expression through the ERK–MEK pathway in cancer cells by direct binding of early growth responsive protein 1 (Egr-1) to the Id promoter." (PMID 34302526, 2022). "In addition to the EGF and IGF systems, PDGF and basic FGF (bFGF) act as survival factors in cancer cells by engaging stimulatory signaling mechanisms mediated by HIF-1α." (PMID 35158804, 2022). "GSVA pathway analysis revealed differentially regulated cancer pathways between the three m5C-clusters, including KRAS-related pathways (MAPK-, mTOR-, EGF- and ERK-pathways), cell death pathways (TNFR1-, FAS- and death-pathways), and cancer-related pathways (Wnt-, Gleevec-, MET and CREB-pathways)." (PMID 36060802, 2022). "Keeping this in mind, and regarding the lack of growth factors in the media due to the starved context, the presence of EGF at the ULD of 27 CH could have reinforced the inhibition of the EGFR pathway, which is rightly involved in cancer-cells metabolism." (PMID 35682738, 2022). "The activation of M2 macrophages and CAFs can be triggered by cytokines secreted from cancer cells, e.g., TGF-β, and multiple receptor tyrosine kinase signaling ligands, such as FGF and PDGF, while they can also be stimulated to secrete EGF, thereby enhancing the invasion of EOC." (PMID 36553542, 2022). "We have partitioned this multi-component review into different sections in which we summarized landmark research-works which highlighted betulinic acid mediated regulation of JAK/STAT, VEGF, EGF/EGFR, TRAIL/TRAIL-R, AKT/mTOR and ubiquitination pathways in the inhibition of cancer." (PMID 36615262, 2022). "We hypothesize that the smart combination of CIMAVax-EGF with the established EGFR TKI and ICIs can further contribute to the transition of advanced cancer to a chronic disease, compatible with years of quality life." (PMID 34211836, 2021). "One of the FOXP2 down-regulation mechanisms during the EGF-induced EMT might be mediated by the key mesenchymal transcription factor TWIST, whose levels were stimulated by EGF treatment in cancer cells." (PMID 33718155, 2021). "Indeed, cancer cell migration is enhanced by perivascular TAMs involving a paracrine loop of TAMs CSF1 secretion and epidermal growth factor (EGF) secretion by cancer cells." (PMID 33783686, 2021). "Among the downregulated cancer-related pathways herein, Ras, PI3K, VEGF, fibroblast growth factor, and epidermal growth factor are all activated by HBx in HCC, and all crosstalk with NF-κB, suggesting that NF-κB inhibition may also occur." (PMID 33945993, 2021). "Cancer-cell-derived M-CSF and TAM-derived EGF promote cancer cell migration along collagen fibers to aggregate around vasculature, and TAMs further release proteolytic enzymes such as MMPs, which destroy the extracellular matrix, promoting the dissemination of tumor cells." (PMID 34638388, 2021). "Cancer cells secrete a number of angiogenicfactors (VEGF, EGF and interleukin-18)." (PMID 34455718, 2021). "al. reported an enzyme prodrug system (Fcy-EGF/5-FC), which is a fusion protein composed yeast cytosine deaminase fused with human epidermal growth factor (Fcy-hEGF) and capable of targeting and killing EGFR-overexpressing cancer through converting 5-FC to 1000-fold toxic 5-FU." (PMID 33672989, 2021).
cancer (continued). "Neutralizing antibodies against five arbitrarily selected pleiotropic proteins present in MAs (TGF-β1, HGF, EGF, IGF-1, GRO-1) were used to check whether inhibition of these agents translates to decreased adhesion of cancer cells to PMCs or PFBs." (PMID 33921783, 2021). "According to GO term analysis, genes correlated with MBNL2 were significantly enriched for biological processes associated with membrane trafficking, TGF-beta signaling, VEGFR and EGF/EGFR signaling, which are all related to cancer cell invasion and metastasis." (PMID 34659561, 2021). "Contrary to M1, M2 TAMs participate in Th2 response and cancer progression and affect anticancer therapies via the secretion of the immunosuppressive cytokine such as TGF-β and mitogenic growth factors, including PDGF and epidermal growth factor." (PMID 33129234, 2021). "For instance, a mutated PA83 variant unable to bind to its native receptors due to mutations in the receptor-binding domain (termed mPA83), was fused to EGF (epidermal growth factor) and thus redirected to EGF receptors (EGFR), which are highly expressed in many cancer cells." (PMID 34733166, 2021). "In cancer, macropinocytosis can be driven not only by oncogenes, such as RAS and SRC, but can also be stimulated by growth factors (e.g., EGF), and/or ruffling kinase (e.g., p21-activated kinase-1) to modulate cancer cell metabolism and nutrient internalization." (PMID 34112916, 2021). "TAM M2 macrophages express molecules that can directly affect cancer cell proliferation including members of the fibroblast growth factor (FGF) family, namely transforming growth factor beta (TGF-β) and epidermal growth factor (EGF)." (PMID 34209703, 2021). "The inhibition of EGF/EGFR signaling pathway by oridonin results in the suppression of ERK and FAK leading to a decrease in cell motility, migration, and invasion capacities of cancer cells." (PMID 33546106, 2021). "Additionally, in vitro culture of CRC organoids requires some crucial growth factors, including epidermal growth factor (EGF), which promotes the proliferation of cancer cells." (PMID 35155215, 2021). "In carcinoma cells, inhibition of gC1qR with a monoclonal antibody is known to reduce EGFR phosphorylation and block stimulation of migration and formation of lamellipodia in response to EGF." (PMID 34724825, 2021). "In many carcinomas, together with TGF-β and interleukins signaling, hepatocyte growth factor (HGF), basic fibroblast growth factor (bFGF), epidermal growth factor (EGF) and PDGF also play a role in the induction of transcription factors responsible for EMT progression." (PMID 33407613, 2021). "Binding of the anti-EGFR sdAbs to the EGFR extracellular domain may prevent EGF from binding to EGFR, or homophilic cancer cell–cell adhesion through cell surface EGFR interaction." (PMID 33023595, 2020). "Later on, the enhanced expression of the SASP factors CXCL12, HGF, MMPs and TGFβ in irradiated fibroblasts was reported to increase EMT and invasiveness of cancer cells, and enhanced expression of the SASP factors EGF, FGF-4, GM-CSF, IGF-1,2, IGFBP-2,4,6 induced chemoradioresistance in cancer cells." (PMID 32384619, 2020). "We assessed four different cancer cell lines capable of undergoing an EMT (A549, lung; DU145, prostate; MCF7, breast; and OVCA420, ovarian) and exposed each to known EMT-inducing factors: TGFB1, EGF, and TNF." (PMID 32358524, 2020). "If this ratio is low, it is likely that the concentration of EGF secreted by CAFs is not sufficient to rescue cancer cells from cetuximab treatment." (PMID 32481658, 2020). "Also, several studies have shown that EGF-EGFR signaling pathway plays important roles in maintenance, proliferation, and self-renewal of cancer stem cells." (PMID 32376896, 2020). "In addition, EGF is known as a major regulator of EMT/MET and is one of the most established targets of cancer treatment." (PMID 33202923, 2020).
cancer (continued). "Constructed with a substrate sensitive to MT1-MMP, the first MT1-MMP FRET sensor observed epidermal growth factor (EGF)-induced, cytoskeleton-dependent MT1-MMP activity at the leading edge of migrating cancer cells, which can be abolished by tissue inhibitor of metalloproteinase-2 (TIMP-2)." (PMID 33240867, 2020). "According to Condeelis and Pollard, other processes that lead to cancer progression are angiogenesis (VEGF, ADM, PDGF, MMPs, TGF-β, CCLa, SEMA3A), intravasation, and extravasation (EGF, CCL-18, P2Y2 receptor), migration and invasion (MMPs, serine proteases, cathepsins, MIP-1β, EGF)." (PMID 32477352, 2020). "The results of this study clearly demonstrate a unique relationship between EGF signaling and WNT7A expression in regulating cancer cell migration, which could be essential in the identification of therapeutic targets for the treatment of OSCC." (PMID 32174831, 2020). "Then, we investigated the effect of both non-conjugated and EGF-TiO2 PEG NPs on cancer cell line proliferation and growth via the investigation of EGFR localization and expression." (PMID 33003324, 2020). "Binding of EGFR with its ligands TGFα or EGF results in autophosphorylation of RTK followed by activation of downstream pathways, including the RAS pathway, that regulate cell proliferation and differentiation in various types of cancer." (PMID 32432044, 2020). "Again, to address the specificity of BMP-2 and to distinguish MBT from cancer cell-intrinsic migration mechanisms, we also performed a similar experiment using EGF to replace BMP2 and found no significant reduction of EGF-induced cell migration from CBX." (PMID 32964116, 2020). "In particular, PGE2 and EGF/EGFR may cooperate to promote growth, invasion, epithelial mesenchymal transition (EMT), and a stem-like phenotype of cancer cells." (PMID 33271839, 2020). "Besides α5β1 integrin, NRP1 co-interacts EGF with EGFR, and HGF with c-Met, and activates these pathways which participate in the proliferation of cancer cells." (PMID 32560565, 2020). "Indeed, the actinoporin delayed the EGF-induced neoplastic transformation of JB6 Cl41 cells and suppressed colony formation of all cancer cell lines, with the inhibition level of HT-29 and SK-MEL-28 cells comparable to cisplatin." (PMID 33348592, 2020). "It has been documented that cancer cells may gain invasive and migratory properties when they receive TME signals such as EGF, VEGF, TNF-α, and TNF-β, which could promote tumorigenesis and metastasis." (PMID 32174831, 2020). "Panc-1 and BxPC-3 were pretreated with resveratrol at different concentrations (50 and 100 μM) for 24 h and then inoculated in serum-free DMEM/F12 medium (containing 20 ng/ml EGF, 20 ng/ml FGF, and 1% B27) for 1 week to determine the ability of the cancer cells to form pellets." (PMID 32766132, 2020). "Using EGFR-expressing human adenocarcinoma MCF-7 cells, we demonstrated that in contrast to MNT with N-terminal epidermal growth factor (EGF), MNTN-affibody and MNT with EGF on the C-terminus did not stimulate cancer cell proliferation." (PMID 32194412, 2020). "Importantly, fibroblast-derived EVs induce cell proliferation in epidermal growth factor (EGF)-dependent patient-derived organoids, one of the best current systems to model the intra-tumoral heterogeneity of human cancers." (PMID 32775326, 2020). "Moreover, additive growth factors for tumorsphere formation, such as EGF and IL6, can phosphorylate STAT3 in cancer cells." (PMID 33023006, 2020). "It was also showed that the EGF-conjugated GNPs alone, incubated for 4 h, did not reduce the cells’ viability (%), which also confirms their safety and inefficacy as anti-cancer therapy." (PMID 33353068, 2020). "Furthermore, TAMs are the major source of growth factors in the TME, such as VEGF-A, placenta growth factor (PlGF), epidermal growth factor (EGF), fibroblast growth factor (FGF), which all support cancer cells proliferation and survival." (PMID 33212945, 2020).